ENSG00000264066 (novel transcript)
Gene: Long non-coding RNA gene on chromosome 17 (28,860,897 to 28,861,998, reverse strand). Ensembl gene ENSG00000264066.
Gene Ontology:
Biological process: miRNA-mediated post-transcriptional gene silencing
Cellular component: RISC complex